RNU7-65P (RNA, U7 small nuclear 65 pseudogene)
Synonyms: U7.65
Gene: Small nuclear RNA gene on chromosome 6 (49,344,800 to 49,344,861, reverse strand). Ensembl gene ENSG00000252457.
Homologues: Orthologues: chimpanzee U7 (100% identical), macaque U7 (100% identical), pig U7 (82% identical). Paralogues in human: U7 (90% identical), RNU7-60P (89% identical), RNU7-84P (89% identical), RNU7-188P (85% identical), RNU7-2P (85% identical), RNU7-52P (85% identical), RNU7-55P (85% identical), RNU7-56P (85% identical), RNU7-71P (85% identical), RNU7-1 (84% identical), RNU7-12P (84% identical), RNU7-13P (84% identical), and 142 more.